FOXP3 (forkhead box P3)
Diseases named in the same sentence as FOXP3 in open-access papers (continued):
Sharing a sentence is not in itself a finding about the gene and the disease.
helminth infections (continued). "More studies showed that helminth infection rapidly expanded natural CD4+Foxp3+ regulatory T cells (tTregs) to inhibit host protective immunity against helminth infection while adaptive pTregs were differentiated slowly with limited protection against helminth infection." (PMID 34336843, 2021). "But unlike the elevated numbers of Foxp3‐expressing regulatory T cells reported with helminth infections, we observed fewer CD4+/Foxp3+ Treg cells in the colons of mice with FMT-P." (PMID 39466773, 2024). "Consistent with previous reports on helminth infections or their products being able to induce the production of Tregs, we discovered that the proportion of CD4+CD25+Foxp3+Tregs in the spleen was increased in SJMHE1‐treated mice." (PMID 31496071, 2019). "In line with the role of Treg cells in helminth infection, NOTCH1 has recently been shown to be involved in Treg function and to cooperate with TGFb for regulation of the FOXP3 promoter." (PMID 20807397, 2010). "Some studies investigating T cell responses following various helminth infections have also previously reported induction of both classical FOXP3+IL-10+ and non-conventional FOXP3-IL-10+ regulatory T cells." (PMID 35720355, 2022). "In one study on recent immigrants to the UK, those patients with helminth infection showed a significant increase in CD4+ FOXP3+ regulatory T cells compared to those without helminth infection." (PMID 31294001, 2019). "In contrast to other helminth infections, S. mansoni did not elicit a Foxp3+ Treg cell response during this early phase of infection." (PMID 26195548, 2015). "The expansion of CD4+Foxp3− Teff cells was also reduced in the absence of ICOS as observed in other helminth infections 28–31." (PMID 23319295, 2013). "Since AAMφ and Foxp3+ T cells are both important in regulating the immune response during helminth infection it is perhaps not a surprise that AAMφ can induce the differentiation of Foxp3+ T cells." (PMID 22927819, 2012). "In this study we were able to characterise naturally occurring regulatory T cells in a human helminth infection with a more comprehensive marker set, namely CD4+(dim)CD25+(high)FOXP3+CD127low cells and analysed the relationship to activated T cells designated as CD4+CD25+FOXP3−." (PMID 21347311, 2011). "Irrespective of the degree of IL-4Rα deletion within the Foxp3+ Treg cell population, mice showed exacerbation of immune effector responses with aggravated tissue pathology in tissue-dwelling helminth infections (Schistosoma mansoni or Nippostrongylus brasiliensis)." (PMID 30379806, 2018). "Therefore, in contrast to the case for other helminth infections, early-stage S. mansoni infection does not induce the expansion of Foxp3+ Treg cells in the infection site, draining LN, or spleen." (PMID 26195548, 2015).
food allergy (41 papers, 2010 to 2025). Gastrointestinal disturbances, skin eruptions, or shock due to allergic reactions to allergens in food. "TGF-β derived from Foxp3+RORγt+ Tregs was shown to restrain mast cell and IgE responses and, thus, diminish the susceptibility to food allergy." (PMID 37936708, 2023). "The expression pattern of transcription factor Forkhead Box Protein 3 (FOXP3) in Tregs was shown to be associated with the IgE-dependent food allergy and acquisition of tolerance in infants with cow’s milk allergy." (PMID 37520545, 2023). "In humans, Treg cells are known to be an important element in reducing allergic inflammation as a mutation in the FOXP3 gene is associated with severe eczema, food allergy and high levels of IgE and eosinophilia." (PMID 22347409, 2012). "Moreover, WASp-deficient FOXP3+ Tregs has been shown to drive Th2-mediated intestinal inflammation and food allergy, marked by increased GATA-3, IL-4, and IgE levels." (PMID 41035657, 2025). "Insufficient vitamin D levels might lower the Tregs through a change in methylation of FOXP3 and determine an increased susceptibility to food allergy." (PMID 35565735, 2022). "Indeed, mutations within the FOXP3 locus are associated with the development of severe food allergies due to a widespread loss of tolerance to innocuous antigens." (PMID 34887847, 2021). "Foxp3+ Treg cells play a central role in installing oral tolerance, as evidenced by the fact that loss-of-function mutations affecting Foxp3 in mice and humans result in spontaneous severe allergic inflammation, such as food allergies (FA)." (PMID 33193456, 2020). "Interestingly, the Foxp3/Rorγt (except for the treated group)and Foxp3/Gata3 ratios were significantly increased in the groups received C. butyricum orally as compared to the food allergy group indicating an increase in Treg-associated responses." (PMID 28250847, 2017). "A variant of IPEX syndrome, which is characterised by autoimmune and severe allergic symptoms, including severe enteropathy, food allergies, atopic dermatitis, hyper-IgE and eosinophilia, is associated with a mutation within an upstream non-coding region of Foxp3 that affects its function." (PMID 23739144, 2013). "It has been reported that RA increases the expression of anti-inflammatory cytokines IL-6 and FOXP3 and increases the expression of pro-inflammatory cytokines in rats, in which a food allergy model was created with ovalbumin." (PMID 39770446, 2024). "Even if this is not the case, the Chatila study provides clear evidence that Foxp3+ T cells develop into IL-4–expressing cells in food allergy and that this IL-4 can drive IgE responses." (PMID 39377224, 2024). "Children with IgE-mediated food allergy have significantly lower FOXP3 expression compared to healthy controls, and decreased frequencies in circulating TREG cells after allergen exposure." (PMID 34887847, 2021). "These Th2-like Foxp3+ Treg cells, which express Th2-related transcription factors and cytokines, exacerbate food allergy symptoms." (PMID 33584704, 2020). "At last, oral immunotherapy, the only known therapy for food allergies, increases Treg cell function, hypomethylation of FOXP3 gene and the number of FOXP3 positive cells." (PMID 30619299, 2018). "It was shown that children with IgE mediated food allergy have significantly lower FOXP3 expression compared to healthy controls and children with peanut or egg allergy showed a decrease in Treg cell percentage after allergen exposure." (PMID 30619299, 2018). "Epicutaneous immunotherapy (EPIT) has been proposed as an attractive strategy to actively treat food allergy and has been shown to induce tolerance in sensitized mice through the induction of Foxp3+ regulatory T cells (Tregs), especially CD62L+ Tregs." (PMID 30233572, 2018). "Compared to the food allergy group, Tbet expression was increased in the treated group, however, the expression of Foxp3 remained unchanged." (PMID 28250847, 2017).
food allergy (continued). "The expression of Th1-(Tbet) and Treg-(Foxp3) transcription factors was significantly decreased in the food allergy group as compared to the control group, whereas the expression of Th2-(Gata3) and Th17-(Rorγt) transcription factors increased dramatically." (PMID 28250847, 2017). "Foxp3+ regulatory T cells have been shown to be suppressive in other models of allergen immunotherapy for food allergy and future studies should investigate their role in the context of algal‐produced allergens." (PMID 26801740, 2016). "With regard to food allergy, the frequency of Foxp3+ cells in the periphery is low in individuals with food allergies, and children with food allergy have reduced T-regulatory cell function." (PMID 23739144, 2013). "Another recent report however, contradict to such tolerogenic effects of Foxp3 in food allergy, where Foxp3 along with Nfat-C2, IL-16 and Gata-3 genes were reported to up-regulated in children with persisting cow's milk allergy." (PMID 21211037, 2011). "Furthermore, the success of experimental therapy of Th2-driven food allergy with two different bacterial consortia, consisting of either Clostridiales or Bacteroidales species, required RORγt expression in Foxp3+ Tregs." (PMID 33531385, 2021). "Similarly, patients with dysregulation in FoxP3+ Treg (Immune dysregulation, polyendocrinopathy, X-linked; IPEX) develop food allergies among other GI and immune pathologies." (PMID 32466620, 2020). "Furthermore, it was recently reported that baicalein effectively attenuated the symptoms of food allergy through its dual functions of the induction of CD4 + Foxp3 + T cells and enhancement of intestinal barrier function." (PMID 29143798, 2017). "Therefore, Bc-specific induction of CD4+Foxp3+ Tregs not only inhibits Th2 inflammation and anaphylaxis, but also suppresses Th17 pro-inflammatory responses in this mouse model of food allergy to ST." (PMID 28512288, 2017). "Taken together, mesenteric IL-10-producing regulatory B cells control food allergy via Foxp3+ regulatory T cells and could potentially act as a therapeutic regulator for food allergy." (PMID 26785945, 2016). "Moreover, polymorphisms in the IL4RA locus have been linked to the pathogenesis of human food allergy, and analogously, reprogramed cells (Foxp3+ TREG → Th2) were also found in the peripheral blood of children with food allergy." (PMID 26347740, 2015). "The role of Foxp3+/CD25+/CD4+ Tregs in development of food allergy is at present unclear." (PMID 22203855, 2012). "Recent studies indicate that Foxp3+ T regulatory cells may play a protective role in food allergy, and Foxp3 is considered an immunophenotype marker of T regulatory cells." (PMID 21211037, 2011). "Additionally, the investigators showed that increased food diversity was associated with an increased expression of forkhead box protein 3 (Foxp3), a marker for regulatory T cells (Tregs), suggesting a protective effect of a diverse diet against food allergy development." (PMID 32466620, 2020). "In previous studies on Treg stability during tolerance acquisition in individuals with food allergy, CD137 expression by Tregs has been suggested to be a marker of enhanced Foxp3 expression and stability." (PMID 40446078, 2025). "The analysis of peripheral blood mononuclear cells (PBMCs) from children with food allergy highlighted that butyrate increases IL-10, IFN-γ, and FOXP3 expression by epigenetic modifications." (PMID 35565735, 2022). "In peripheral blood mononuclear cells (PBMCs) from children with food allergy, butyrate enhanced IL-10, IFN-γ, and Forkhead box P3 (FOXP3) expression through epigenetic mechanisms." (PMID 33922797, 2021). "In this study, we examined the anti-allergic effects of baicalein in a mouse model of food allergy, on the differentiation of naïve CD4+ T cells to Treg cells via Foxp3 induction, and on intestinal barrier function via the regulation of TJs." (PMID 27561877, 2016).
food allergy (continued). "In a mouse model study, administration of baicalein at a dose of 20 mg kg−1 to mice with ovalbumin-induced food allergy alleviated the symptoms of food allergy and reduced the level of serum IgE and effector T cells by induction of CD4+Foxp3+T cell differentiation." (PMID 36902160, 2023). "Food allergy mice had a lower percentage of CD4+ CD25+ Foxp3+ T cells in the MLN compared to nonsensitized controls." (PMID 28250847, 2017). "The adoptive transfer of CD4+CD25+FoxP3+ Treg confined the protection mechanism and the depletion of CD25+ T cells resulted in pronounced disease exacerbation, thus confirming that Treg have an essential role in resolving food allergy in our model." (PMID 26517875, 2015). "The levels of transcription factor FoxP3 and cytokines TGF-β, IL-17A, and IL-23 were not measured in the children with food allergy." (PMID 30651897, 2018). "Although the proportion of FoxP3+ cells among CD4 T cells did not vary, food allergies occurred more rapidly after liver grafting in patients who received basiliximab, raising questions as to Treg functionality in vivo in the absence of functional CD25." (PMID 20689592, 2010). "Foxp3+ TFH cells may be part of a negative feedback mechanism for the GC response, but it’s not clear if they have other functions or if they are present in TFR cells in our food allergy model." (PMID 39377224, 2024).
Crohn disease (40 papers, 2011 to 2025). A gastrointestinal disorder characterized by chronic inflammation involving all layers of the intestinal wall, noncaseating granulomas affecting the intestinal wall and regional lymph nodes, and transmural fibrosis. "The present study aimed to assess the association of Crohn's disease (CD) with Foxp3 polymorphisms and its colonic expression in Chinese patients." (PMID 30710380, 2019). "Here, we analyzed biopsies obtained from Crohn’s disease patients and determined the levels of FOXP3 mRNA splice variants and cytokine mRNA expression." (PMID 26441347, 2015). "A recent study identified FOXP3 +IL-17A+ Treg cells in the intestinal lamina propria of Crohn’s disease patients." (PMID 37615438, 2023). "The results of the study stated that the level of FOXP3 Treg cell was significantly higher in the group of patients with intestinal tuberculosis when compared with Crohn's disease." (PMID 35227196, 2022). "Several previous studies stated several cutoff values of FOXP3 Treg cell levels which were considered significant to distinguish intestinal tuberculosis and Crohn's disease." (PMID 35227196, 2022). "In general, FOXP3 Treg of peripheral blood is lower in patients with Crohn's disease patients, but higher when it was performed on the intestinal biopsy specimens." (PMID 35227196, 2022). "CB2R expression is preferentially induced in FOXP3+Treg-cells and the agonist GP1a enhances FOXP3+Treg immunosuppressive function in Crohn’s disease." (PMID 35115945, 2021). "Even more, CD4+ Foxp3+ T regs from inflamed tissue of Crohn’s disease patients were able to produce IL17 and IFNγ while retaining suppressive function." (PMID 34707610, 2021). "Although the same scenario is seen on CD8+ Tc1 in Crohn ́s disease versus ulcerative colitis, patients suffering from ulcerative colitis have a higher frequency of Tc17 and Foxp3+ IL17+ CD8+ T cells in lamina propria compared to Crohn ́s disease patients." (PMID 34707610, 2021). "Increased level of CD4+CD25+FOXP3+ T regulatory cells has been reported in Crohn’s disease and intestinal tuberculosis patients." (PMID 35153741, 2021). "The lncRNA DQ786243 affects the expression of cAMP response element binding protein (CREB) and Foxp3 by Treg cells in Crohn's disease." (PMID 30546835, 2018). "Having determined that patients suffering from Crohn’s disease had an increased frequency of exon 7 splicing in FOXP3 mRNA, we went on to identify factors that modulate the alternative splicing of FOXP3 in human Treg cells." (PMID 26441347, 2015). "A recent small study in children with Crohn ́s disease showed increased Foxp3+ Treg in the colon of patients receiving Infliximab compared to those receiving other medications." (PMID 22849659, 2012). "Detection of circulating double-positive FOXP3+IL-17A+ CD4+ T cell subsets supports that T cell plasticity may reflect the inflammatory context of Crohn’s disease." (PMID 36405740, 2022). "Moreover, adoptive transfer of OVA-specific Foxp3+ CD25+ CD62Llow CD127low CD4+ T regs into refractory Crohn ́s disease patients was well tolerated and showed a clinical improvement." (PMID 34707610, 2021). "Recent work in Crohn's disease also raises the intriguing possibility that the Foxp3+ cells in the mucosa may also be producing IL-17, and so may not be fully committed to either the TH17 or Treg phenotypes." (PMID 21949691, 2011). "Foxp3+ IL17+ CD8+ T cells were found in lamina propria ́s inflamed mucosa of IBD patients and were increased in ulcerative colitis compared to Crohn ́s disease patients." (PMID 34707610, 2021). "On the other hand, anti-Th17 Treg cells co-expressing IL-17 and Foxp3 were shown to suppress CD4+ T cell proliferation, and found in the inflamed intestinal mucosa of patients with Crohn ́s Disease." (PMID 33542719, 2020). "Notably, Foxp3 expressing CD4+ T cells, belong to Treg, were also able to secret IL-17 in Crohn’s disease, indicating a crossover between Th17 and Treg." (PMID 37063924, 2023).
Crohn disease (continued). "Exposure to UCB alone significantly increased the frequency of CD39+ cells and that of FOXP3+ and IL-10+ cells among Th17 lymphocytes in controls but not in patients with Crohn’s disease." (PMID 36131123, 2022). "The human colonic mucosa contains regulatory type 1-like (Tr1-like, i.e., IL-10-secreting and Foxp3-negative) T cells specific for the gut Clostridium Faecalibacterium prausnitzii (F. prausnitzii), which are both decreased in Crohn's disease patients." (PMID 30787928, 2019). "We also found that patients with Crohn’s disease express increased levels of FOXP3 transcripts lacking exon 7, which correlate with disease severity and IL-17 production." (PMID 26441347, 2015). "However, IL-1β strongly induces alternative splicing of FOXP3 exon 7 in Treg cells and expression of FOXP3 lacking exon 7 is elevated in colon biopsies obtained from Crohn's disease patients." (PMID 33194927, 2020). "The c-Maf expressing RORγt+ Foxp3+ Treg population is also present in human colon but do not show any variation in proportion of total CD4 T cells when comparing colon from patients with Crohn's disease and healthy tissues." (PMID 32117317, 2020). "Moreover, IL-17 mRNA does not correlate with FOXP3 transcripts expressing or lacking exon 2 in biopsies obtained from patients with Crohn’s disease or peripheral blood from patients with coronary artery disease." (PMID 29593749, 2018). "Furthermore, the expression of IL17A mRNA and FOXP3 transcripts lacking exon 7 correlates in Crohn’s disease biopsies and peripheral blood from coronary artery disease patients, indicating that skipping of exon 7 is a common event for IL-17 expression in diverse settings." (PMID 29593749, 2018). "The total amount of FOXP3 mRNA was 0.11 ± 0.026 arbitrary units (mean ± SEM, n = 11) in Crohn’s disease patients, which did not significantly differ (two-tailed unpaired Student’s t test) from the levels found, 0.095 ± 0.018 (mean ± SEM, n = 10), in healthy donors." (PMID 26441347, 2015).